PARP12 (poly(ADP-ribose) polymerase family member 12)
Description:
Mono-ADP-ribosyltransferase that mediates mono-ADP-ribosylation of target proteins. Acts as an antiviral factor by cooperating with PARP11 to suppress Zika virus replication. Displays anti-alphavirus activity during IFN-gamma immune activation by directly ADP-ribosylating the alphaviral non-structural proteins nsP3 and nsP4. Acts as a component of the PRKD1-driven regulatory cascade that selectively controls a major branch of the basolateral transport pathway by catalyzing the MARylation of GOLGA1. Acts also as a key regulator of mitochondrial function, protein translation, and inflammation. Inhibits PINK1/Parkin-dependent mitophagy and promotes cartilage degeneration by inhibiting the ubiquitination and SUMOylation of MFN1/2 by upregulating ISG15 and ISGylation.
Synonyms: ARTD12; PARP-12; ZC3HDC1; FLJ22693; ZC3H1; MST109; MSTP109
Tractability: Small molecule: a structure with a bound ligand is known; a high-quality ligand is known; it has a high-quality binding pocket. PROTAC: ubiquitination databases record sites on it; its protein half-life has been measured; a small molecule that binds it is known.
Target class: Enzyme; Transferase
Gene: Protein-coding gene on chromosome 7 (140,023,746 to 140,063,344, reverse strand). Ensembl gene ENSG00000059378.
Subcellular location: Nucleus; Golgi apparatus, trans- Golgi network; Cytoplasm, Stress granule
Subcellular location (Human Protein Atlas): Nucleoplasm
Gene Ontology:
Molecular function: NAD+-protein mono-ADP-ribosyltransferase activity; NAD+-protein-aspartate ADP-ribosyltransferase activity; NAD+-protein-cysteine ADP-ribosyltransferase activity; RNA binding; NAD+ poly-ADP-ribosyltransferase activity; metal ion binding
Biological process: protein auto-ADP-ribosylation; transepithelial transport
Cellular component: trans-Golgi network; nucleus; cytoplasm; cytoplasmic stress granule; Golgi apparatus
Genetic constraint (gnomAD): Loss-of-function variants: 59 observed, 71.68 expected, observed/expected ratio (o/e) 0.82, 90% interval 0.67 to 1.02. The upper end of that interval is the gene's LOEUF score, 1.02, which puts it in group 4 of 6, group 1 being the genes least tolerant of losing a copy. Missense variants: 850 observed, 863.87 expected, observed/expected ratio (o/e) 0.98, 90% interval 0.93 to 1.04. Synonymous variants: 403 observed, 347.26 expected, observed/expected ratio (o/e) 1.16, 90% interval 1.07 to 1.26.
Homologues: Orthologues: chimpanzee PARP12 (99% identical), macaque PARP12 (98% identical), dog PARP12 (84% identical), rat Parp12 (82% identical), mouse Parp12 (81% identical), pig PARP12 (75% identical), guinea pig PARP12 (67% identical), rabbit PARP12 (63% identical), zebrafish parp12a (41% identical). Paralogues in human: ZC3HAV1 (33% identical), TIPARP (23% identical), PARP14 (20% identical), PARP11 (17% identical), PARP15 (14% identical), PARP10 (13% identical), ZC3HAV1L (13% identical), PARP9 (12% identical).
Diseases named in the same sentence as PARP12 in open-access papers:
PARP12 is named in the same sentence as 30 diseases in open-access papers, as found by Europe PMC text mining. Sharing a sentence is not in itself a finding about the gene and the disease. The quoted sentences say what the papers report.
viral infection (11 papers, 2020 to 2025). "In addition to disrupting the virus particle assembly, PARP12 can also suppress virus infection by MARylating viral proteins and causing their degradation." (PMID 36035988, 2022). "Upon viral infection, Poly-(ADP-Ribose) Polymerase 12 (PARP12) can be recruited to initiation factors to modulate the translation machinery and inhibit translation globally." (PMID 39066259, 2024). "PARP1–3 are activated by DNA damage, whereas the mono-ARTs PARP10, PARP11 and PARP12 are upregulated during viral infection leading to translational shut-down." (PMID 36018800, 2022). "A functional role of PARP12 in SG biology granules has yet to be found, but as SGs are discussed as first line response to viral infections, the regulation and/or modulation of these condensates might be one mode of antiviral action of PARP12." (PMID 36986379, 2023). "The best-characterized function of PARP12 is its role in virus infection." (PMID 36035988, 2022). "For example, PARP12 was identified as an interferon-induced gene playing a potential role in cellular defenses against viral infections; its association with p62/SQSTM1 correlates with increased NF-kB signaling, suggesting the contribution of PARP12 to inflammation." (PMID 32900001, 2020). "The results revealed that, upon viral infection, the mRNA levels of NAD+-consuming enzymes, including Sirt1-7, Parp1, Parp10, Parp12, Parp14, and CD38, were substantially upregulated." (PMID 40006932, 2025). "PARP12 is a representative ISG that inhibits viral replication via ADP-ribosylation, while IFI44L is an interferon-inducible gene that is upregulated upon viral infection." (PMID 41465783, 2025). "PARP12 and PARP14, as interferon-induced genes (ISG), were found to block RNA translation of viruses and played a potential role in cellular defenses against viral infections." (PMID 38543614, 2024). "Interestingly, RanBP9-3xHA pulled down Parp12 (Poly[ADP-ribose] polymerase member 12), which had been previously reported as RanBP9 interactor, and is an interferon stimulated gene that contributes to suppressing viral infections." (PMID 40223093, 2025). "For instance, transcriptional induction of noncanonical PARP isoforms (e.g., PARP10, PARP12), along with NAD+ depletion, has been observed across viral infections, including coronaviruses, where similar activation of MARylating PARPs contributes to NAD+ loss." (PMID 41362627, 2025).
breast carcinoma (8 papers, 2016 to 2025). "Although the molecular mechanism underlying PARP12 role in breast cancer is not completely understood, it is considered a potential promising novel target in breast cancer therapy." (PMID 39189367, 2024). "PARP12 has been identified as a key factor in causing breast cancer resistance to genotoxic stress." (PMID 39847113, 2025). "Although the molecular mechanisms underpinning the role of PARP12 in breast cancer are still being elucidated, these findings highlight its potential as a promising therapeutic target in breast cancer treatment." (PMID 40741921, 2025). "Along with these roles, PARP12 has been identified as one of the main factors involved in the acquisition of breast-cancer resistance to chemotherapy, evidenced through a delayed cancer cell colony regrowth upon transcriptional inhibition of PARP12." (PMID 39847113, 2025). "The present study investigates PARP12 function in breast cancer cells, to clarify the molecular details of PARP12’s role in enhanced cell survival." (PMID 39847113, 2025). "Despite these limitations, our work lays a critical foundation for understanding the role of PARP12 in breast cancer biology." (PMID 39847113, 2025). "In the context of breast cancer, PARP12 has been identified as an active participant in the IFN–STAT1 signaling pathway, which promotes survival and regrowth of breast cancer cells after chemotherapy." (PMID 40741921, 2025). "Overall, these data demonstrate a role for PARP12 in cell survival of a subset of ER + breast cancer cells, supporting an involvement of PARP12 in drug-resistance acquisition." (PMID 39847113, 2025). "This phenotype is detectable in ER + breast cancer cells, suggesting an interconnection between the oestrogen receptor and PARP12-driven pathways." (PMID 39847113, 2025). "We identified PARP12 as one such active contributor of this pathway involved in post-chemotherapy survival and re-growth of breast cancer cells." (PMID 27791205, 2016). "Taken together, these data indicated that breast cancer cell intrinsic IFN signaling induced by genotoxic stress favors resistance to treatment in a PARP12-dependent manner." (PMID 27791205, 2016). "Since the PI3K–AKT–FOXO axis is highly active in the development of breast cancer drug-resistance and PARP12 is a positive regulator of this pathway, we propose PARP12 as potential pharmacological target to be exploited to re-sensitize ER + breast cancer to endocrine treatment." (PMID 39847113, 2025). "Here, AKT is described as a novel substrate of PARP12, a mono-ADP-ribosyltransferase acting as a key factor in mediating breast cancer cell survival." (PMID 39847113, 2025). "Here, we demonstrate that PARP12-mediated mono-ADP-ribosylation of AKT is required for AKT activation whilst the absence of PARP12 leads to apoptosis induction in a subset of oestrogen receptor-positive breast cancer cells." (PMID 39847113, 2025). "These analyses also allow us to identify features that help stratify difficult to treat breast cancer subtypes, i.e., GALP, IYD, and PARP12 were all significantly associated with survival in non-senior triple-negative breast cancer patients." (PMID 32241256, 2020). "NR1H3 is a nuclear receptor component and an anti-invasive gene for bladder cancer; PARP12 has been reported to suppress hepatocellular carcinoma metastasis; SAMHD1 is yet another suppressor of epithelial transformation; PSMB9 is a key metastasis suppressor for breast cancer." (PMID 33562461, 2021). "PARP12 localized at the TGN, and not at the cis-Golgi, in all of the cell types tested (e. g., MDA breast cancer cells, THP leukemia monocytes and A375 melanoma cells)." (PMID 29070863, 2017).
hepatocellular carcinoma (6 papers, 2018 to 2025). A malignant tumor that arises from hepatocytes. "While PARP12 has been reported as a tumor suppressor that plays an important role in the suppression of hepatocellular carcinoma metastasis, it has also been implicated in coronary heart disease and associated with vitiligo." (PMID 33578652, 2021). "We also provided evidence that PARP12 deficiency increased the migration and invasion of hepatocellular carcinoma (HCC) cells and promoted HCC metastasis in vivo by regulating the epithelial–mesenchymal transition process." (PMID 30154409, 2018). "PARP12 act as a tumor suppressor that controls hepatocellular carcinoma (HCC) metastasis via regulating the EMT process." (PMID 38734665, 2024). "For instance, PARP12 depletion promotes cell invasion and migration in cell models of hepatocellular carcinoma (HCC), as well as metastasis in vivo." (PMID 41463260, 2025).
COVID-19 (2 papers, 2021 to 2022). A disease caused by infection with severe acute respiratory syndrome coronavirus 2. "Our transcriptomics and qPCR results indicated that a set of PARP family members, including Parp9, Parp10, Parp12, and Parp14, were significantly induced by SARS-CoV-2 infection in mice, similar to those in COVID-19 patients." (PMID 35487885, 2022).
ZIKV infection (2 papers, 2023 to 2024). "PARP12 can suppress Zika virus infection through degradation of NS1 and NS3 viral proteins and cooperation with PARP11." (PMID 39445214, 2024). "Another study demonstrated that PARP11 cooperated with PARP12 in restricting ZIKV infection through enhancing NS1 and NS3 degradation, indicating PARP11 was an anti-virus factor in ZIKV infection." (PMID 39445214, 2024).
colorectal cancer (1 paper, 2025). A primary or metastatic malignant neoplasm that affects the colon or rectum. "To investigate the role of PARP genes in colorectal cancer cell response to ionizing irradiation, we generated PARP12, PARP13, and PARP14 knockout (KO) sublines of DLD1 and HT29 cells using CRISPR/Cas9 gene editing." (PMID 40646573, 2025). "The expression of PARP9, PARP12, PARP13 and PARP14 was particularly elevated in irradiated colorectal cancer HT29 cells in a microenvironment-dependent manner." (PMID 40646573, 2025). "We previously discovered that the multifractionated dose IR upregulated the expression of unconventional PARP family members including PARP9, PARP12, PARP13 and PARP14 in colorectal cancer cells grown in laminin-rich ECM 3D cell culture." (PMID 40646573, 2025). "Moreover, HT29 PARP12(−/−) and PARP13(−/−) spheroids experienced a considerable reduction in size following irradiation, supporting the impact of PARPs on colorectal cancer cell sensitivity to IR in the microenvironment dependent manner." (PMID 40646573, 2025).
myopia (1 paper, 2019). "eQTLs at PARP12 and CLU colocalized with AMD and myopia signals, respectively, under both conditions." (PMID 31123710, 2019).
rectal cancer (1 paper, 2025). A primary or metastatic malignant neoplasm that affects the rectum. "We then explored the distribution of low and high fold of expression after CRT of PARP9, PARP12, PARP13, and PARP14 in both tumor and adjacent normal tissue sample groups from rectal cancer patients." (PMID 40646573, 2025).
rectal tumor (1 paper, 2025). "Taken together, this study demonstrates that CRT significantly increases the expression of PARP9, PARP12, PARP13 and PARP14, specifically in rectal tumor tissue." (PMID 40646573, 2025). "Finally, we demonstrated that chemoradiotherapy significantly upregulates the expression of PARP9, PARP12, PARP13 and PARP14 exclusively within rectal tumor tissues." (PMID 40646573, 2025).
type 1 diabetes (1 paper, 2025). "Here, we studied the role of ADP-ribosyltransferase PARP12 in type 1 diabetes development." (PMID 40470236, 2025).
tumor (12 papers, 2012 to 2025). "Based on this evidence, to understand the molecular mechanism underlying this phenotype, we investigated the impact of PARP12 depletion on apoptosis induction on a broad set of cancer cell lines of varied tumour origin." (PMID 39847113, 2025). "Although changes in PARP12 expression in tumor tissue were significantly associated with lymph node status after CRT, no other statistically significant PARP associations with patient variables were found." (PMID 40646573, 2025). "PARP12 may also have a tumour suppressor function and supporting this, low PARP12 expression levels are associated with tumourigenesis." (PMID 35096828, 2021). "Gene expression profiling confirmed increased expression levels of other members of the ARTD family including Parp9, Parp10, Parp12 and Parp14 in Parp7KO tumours." (PMID 39867896, 2024). "Our results indicated that PARP12 is a tumor suppressor and may be a novel therapeutic option for HCC treatment." (PMID 30154409, 2018). "We then performed a colony assay using the MCF7 model in order to evaluate whether PARP12 silencing interfered with tumor survival and growth." (PMID 27791205, 2016). "For example, PTEN, RBL1, CDKN2AIP, RNASET2A, HINT1, and PARP12 are well-known tumor suppressors and were downregulated or absent in the CT26/SCID tumors." (PMID 38672200, 2024).
infection (8 papers, 2021 to 2025). The state of being infected such as from the introduction of a foreign agent such as serum, vaccine, antigenic substance or organism. "Further work is required to decipher which PARP12/14 target(s) restrict viral protein production or assembly following infection with Mac1 catalytic-mutant CoVs." (PMID 40736256, 2025). "Overexpression of PARP10 and PARP12 decreased EGFP expressing cells as measured by flow cytometry 24 and 48 h post-infection (hpi)." (PMID 36840772, 2023). "We found members of this family upregulated by both VN1203 and BC500 infection in ducks (PARP9, PARP10, PARP12 and PARP14)." (PMID 34804075, 2021). "We recently demonstrated that JHMV N1347A replication is increased following an intracranial infection of PARP12-/- mice compared to WT mice, but not following an intranasal infection." (PMID 40471948, 2025). "However, in mice the absence of PARP12 resulted in several different levels of virus restoration depending on the tissue and route of infection." (PMID 40471948, 2025). "While Mac1-mutant virus had enhanced replication and led to increased disease in PARP12-/- mice following both i.c. and i.p. infections, Mac1-mutant virus replication or disease was not enhanced at all in PARP12-/- mice following an i.n. infection." (PMID 40471948, 2025). "In addition, PARP12, TAP1, CMPK2 and ADAR, which are crucial to restrict RNA virus replication, e.g. DENV、HIV、ZIKV, also upregulated in the early stages of HuB20 infection, indicating multiple antiviral responses was involved in this stage." (PMID 36544767, 2022).
cancer (7 papers, 2016 to 2025). A tumor composed of atypical neoplastic, often pleomorphic cells that invade other tissues. "Aberrant activity (mutation) in PARP12 has been linked to various diseases including inflammation, cardiovascular disease, and cancer." (PMID 36016564, 2022). "PKD activation regulates PARP12 dependent ADP-rybosilation of Golgin 97 on TGN membranes, and both PARP12 and Golgin97 have clear roles in cancer." (PMID 35399533, 2022). "We may speculate that when combined with mafosfamide, PARP12 inhibition reduces dormant cell survival leading to delayed cancer cell colony regrowth." (PMID 27791205, 2016). "Altogether, these preliminary findings suggest that the expression of PARP9, PARP12, PARP13 and PARP14 in irradiated cells is reliant on 3-dimensional cellular microenvironment or cell type, and the PARP expression pattern may be specific to cancer cells." (PMID 40646573, 2025). "Currently, there is no consolidated data on how PARP9, PARP12, PARP13 and PARP14 affect the response to ionizing radiation in cancer cells." (PMID 40646573, 2025).
PARP12 also shares sentences with these, for which no sentence is quoted: glioblastoma (2 papers); osteosarcoma (2); triple-negative breast carcinoma (2); bladder cancer (1); breast tumour (1); cardiovascular disease (1); colon cancer (1); coronary heart disease (1); Ewing sarcoma (1); influenza (1); lung carcinoma (1); melanoma (1); oral squamous cell carcinoma (1); osteoarthritis (1); ovarian carcinoma (1); prostate carcinoma (1); vitiligo (1).